XRCC4 (X-ray repair cross complementing 4)
Diseases named in the same sentence as XRCC4 in open-access papers (continued):
Sharing a sentence is not in itself a finding about the gene and the disease.
ovarian carcinoma (6 papers, 2017 to 2025). A malignant neoplasm originating from the surface ovarian epithelium. "Moreover, using FACS assay to monitor the cell apoptosis, we also found that the loss of XRCC4 robustly induced more cell death in the ovarian cancer cells treated with cisplatin." (PMID 36551554, 2022). "Mice transplanted with XRCC4 WT or Y66F mutant ovarian cancer cells were treated with cisplatin +/− LDHi." (PMID 41462961, 2025). "We further tested this idea in vivo using ID8-luciferase ovarian cancer model, especially considering the XRCC4 Y66F is conserved between human and mice." (PMID 41462961, 2025). "Disrupting this interaction via an XRCC4 Y66 mutation abolishes lactate-induced NHEJ activation and sensitizes ovarian cancer cells to cisplatin in vivo." (PMID 41462961, 2025). "From a clinical perspective, our findings underscore the therapeutic potential of targeting lactate metabolism or the lactate–XRCC4 interaction to overcome chemoresistance in ovarian cancer." (PMID 41462961, 2025). "In this study, we reveal that lactate enhances NHEJ-mediated DNA repair and confers chemoresistance in ovarian cancer by directly facilitating the interaction between XRCC4 and LIG4, the key event in NHEJ machinery assembly." (PMID 41462961, 2025). "We overexpressed the Flag-tagged XRCC4 wild type and Y66F mutant in endogenous XRCC4-depleted ovarian cancer NHEJ reporter cells." (PMID 41462961, 2025). "Taken together, these data demonstrate that XRCC4 expression level positively correlates with cisplatin resistance in ovarian cancer cells." (PMID 36551554, 2022). "Taken together, these data suggest that the cisplatin-activated JNK-cJUN axis contributes to the upregulation of XRCC4 in the cisplatin-resistant ovarian cancer cells exposed to cisplatin." (PMID 36551554, 2022). "To study the role of XRCC4 in the response to cisplatin in ovarian cancer cells, we stably knocked down XRCC4 using two distinct shRNA clones in both the A2780cisR and SKOV3cisR cell lines." (PMID 36551554, 2022). "In this study, through an NHEJ pathway-focused gene RNAi screen, we identified XRCC4 as an important NHEJ factor to promote resistance to cisplatin in ovarian cancer." (PMID 36551554, 2022). "We demonstrated that the knockdown of XRCC4 sensitized cisplatin treatment and the JNK-cJUN axis promotes the upregulation of XRCC4 to confer cisplatin resistance in ovarian cancer cells." (PMID 36551554, 2022). "XRCC4 expression significantly increased in a variety of ovarian cancer cell lines when getting resistant to cisplatin." (PMID 36551554, 2022). "So, the JNK-cJUN complex that mediated the transcription of XRCC4 was also possibly promoted by DGKA in the ovarian cancer cells treated with cisplatin." (PMID 36551554, 2022). "Our data showed that XRCC4 level is significantly correlated with PFS in ovarian cancer patients, and targeting XRCC4 or the upstream kinase JNK strongly attenuated the cisplatin-resistant tumor growth of ovarian cancer cells in the preclinical mouse model." (PMID 36551554, 2022). "Here, through an NHEJ pathway-focused gene RNAi screen, we found that the knockdown of XRCC4 significantly sensitized cisplatin treatment in the platinum-resistant ovarian cancer cell lines." (PMID 36551554, 2022). "In the current study, we demonstrated that XRCC4-mediated NHEJ DNA damage repair also contributes to cisplatin resistance in ovarian cancer." (PMID 36551554, 2022). "Rescued expression of XRCC4 in the XRCC4 knockdown cells significantly reduced the cisplatin-induced DNA damage and restored the resistance to cisplatin in the ovarian cancer cell lines." (PMID 36551554, 2022). "We demonstrated that specific knockdown of XRCC4 significantly induced DNA damage in cisplatin-resistant ovarian cancer upon cisplatin treatment." (PMID 36551554, 2022). "Knockdown of XRCC4 significantly sensitized cisplatin treatment in the platinum-resistant ovarian cancer cell lines." (PMID 36551554, 2022).
ovarian carcinoma (continued). "More importantly, while the knockdown of cJUN abrogated the expression of XRCC4, JNK loss also completely abolished the expression of XRCC4 in cisplatin-resistant ovarian cancer cell lines." (PMID 36551554, 2022). "Through an NHEJ-pathway-focused RNAi screen, we found that XRCC4 specifically sensitized cisplatin treatment in cisplatin-resistant ovarian cancer cell lines, which were further confirmed by a sgRNA-based secondary screen." (PMID 36551554, 2022). "Conversely, highly expressed level of XRCC4 was linked to poor PFS and OS for all ovarian carcinoma patients, and predicted worse PFS and OS for serous, grade III as well as all stages ovarian carcinoma patients." (PMID 34539898, 2021). "To test whether lactate-mediated NHEJ repair played a key role in DNA damage repair and chemoresistance, we compared chemotherapy response in XRCC4-depleted ovarian cancer cells with Flag-tagged XRCC4 wild type and Y66F mutant overexpressed." (PMID 41462961, 2025). "Moreover, we found that the JNK-cJUN axis mediated the transcription and upregulation of XRCC4 in ovarian cancer cells exposed to cisplatin." (PMID 36551554, 2022). "Clinically, our findings support that XRCC4 could serve as a predictive marker and as a promising therapeutic target to treat cisplatin-resistant ovarian cancer." (PMID 36551554, 2022). "To glean a comprehensive mechanistic insight into how XRCC4 is upregulated to promote cisplatin-resistant in ovarian cancer cells, we first used the PROMO database to predict the transcription factors (TFs) that may mediate the transcription of XRCC4." (PMID 36551554, 2022). "Moreover, upregulation of XRCC4 is observed in a panel of platinum-resistant cell lines relative to the parental cell lines, as well as in ovarian cancer patients with poor progression-free survival." (PMID 36551554, 2022). "Here we identify XRCC4 as a critical factor to confer cisplatin resistance in ovarian cancer." (PMID 36551554, 2022). "A similar trend was also observed in the colony formation; the combination of XRCC4 knockdown and cisplatin treatment strongly abolished the colony formation potential in the cisplatin-resistant ovarian cancer cell lines, supporting the role of XRCC4 in the regulation of cisplatin sensitivity." (PMID 36551554, 2022). "Wild-type XRCC4 promoter-luciferase activity (WT) was significantly increased by cJUN overexpression in both the A2780cisR and SKOV3cisR cell lines, suggesting cJUN indeed promotes the expression of XRCC4 in ovarian cancer cells." (PMID 36551554, 2022). "Our study demonstrates XRCC4 in the NHEJ pathway specifically contributes to platinum resistance by mitigating the DNA damage caused by platinum drugs and provides preclinical evidence for targeting XRCC4 as a new strategy to battle cisplatin resistance in ovarian cancer treatment." (PMID 36551554, 2022). "Furthermore, XRCC4 expression and its relationship to cisplatin resistance were further examined in the primary ovarian cancer patient tumor who received platinum-based chemotherapy." (PMID 36551554, 2022). "To further support the cJUN mediate the transcription of XRCC4 in ovarian cancer cells exposed to cisplatin, we perform a ChIP assay to monitor the endogenous binding of cJUN to XRCC4 promoter region in the chromosome in both A2780cisR and SKOV3cisR cell lines treated with cisplatin." (PMID 36551554, 2022). "However, XRCC4 mRNA and protein levels were lower in ovarian cancer cells than that in normal cell line." (PMID 34539898, 2021). "Another reason may be that XRCC4 is more likely to play a different role in different pathological types of ovarian cancer." (PMID 34539898, 2021). "Furthermore, XRCC4 was overexpressed in ovarian carcinomas samples and lowly expressed in normal ovarian samples, and the mean IHC score was 6.00±2.07 in ovarian cancer tissues and 2.13±1.51 in healthy tissues, P<0.0001." (PMID 34539898, 2021).
ovarian carcinoma (continued). "Remarkably, highly expressed mRNA level of XRCC4 was linked to worse PFS and OS in ovarian carcinoma women with all stages (stage I+II: PFS: HR=1.77 (1-3.14), P=0.046, OS: HR=2.6 (1.2-5.65), P=0.012; stage III+IV, PFS: HR=1.23 (1.06-1.43), P=0.0072, OS: HR=1.53 (1.31-1.79), P=0.0000)." (PMID 34539898, 2021). "Notably, the protein level of XRCC2 and XRCC9 were found to be overexpressed in normal ovarian tissues, whereas XRCC4 was highly expressed in patients with ovarian carcinoma, which was consistent with the prognosis of ovarian cancer." (PMID 34539898, 2021). "Furthermore, higher expression of XRCC4 was significantly linked to worse PFS and OS for all ovarian carcinoma women (PFS: HR=1.41 (1.22-1.62), OS: HR=1.56 (1.36-1.8), P=0.0000, P=0.0000)." (PMID 34539898, 2021). "We further observed that XRCC4 loss significantly attenuated cell viability, cisplatin IC50, cell apoptosis, and colony formation in the cisplatin-resistant cell lines treated with cisplatin, confirming the XRCC4 plays an important role in cisplatin resistance in ovarian cancer." (PMID 36551554, 2022). "Interestingly, the function of XRCC4 in ovarian carcinoma remains mysterious." (PMID 34539898, 2021). "In cisplatin-resistant ovarian cancer, the JNK-cJUN complex, activated by cisplatin, translocated into the nucleus and promoted the transcription of XRCC4 to confer cisplatin resistance." (PMID 36551554, 2022). "For XRCC4, its higher level was involved in a worse OS in grade I (HR=3.92 (1.42-10.85), P=0.0049), also a worse PFS and OS in grade III ovarian carcinoma women (PFS: HR=1.38 (1.16-1.65), P=0.0004; OS: HR=1.56 (1.32-1.85), P=0.0000)." (PMID 34539898, 2021). "Consistently, immunofluorescence analysis observed higher staining of XRCC2, XRCC4 and XRCC9 in normal ovarian IOSE cells than that in ovarian carcinomas ES2 cells and OVCAR3 cells." (PMID 34539898, 2021). "The results displayed that XRCC2, XRCC4 and XRCC9 mRNA levels were highly expressed in normal ovarian IOSE cells than in ovarian carcinoma ES2 and OVCAR3 cells." (PMID 34539898, 2021). "With these in mind, only XRCC2, XRCC4 and XRCC9 exhibited consistent results in PFS and OS for all ovarian carcinoma patients." (PMID 34539898, 2021). "Significant expression changes were also confirmed by RT-qPCR for some genes involved in homologous (HR) and non-homologous end joining (NHEJ) DNA damage-repair mechanisms in ovarian cancer, such as XRCC1 in EOC-CC1, and XRCC4, RAD51 and BRCA2 in OSPC2." (PMID 28482906, 2017). "To evaluate the clinical relevance of the study, we applied Kaplan-Meier survival analysis and found that patients with breast or ovarian cancer with high expression of FANCD2 and XRCC4 had poorer overall survival than those with low expression of FANCD2 and XRCC4." (PMID 35642638, 2022). "Our study reveals that the XRCC4 in the NHEJ pathway contributes to platinum resistance by reducing DNA damage and provides preclinical evidence for targeting XRCC4 as a new strategy to overcome cisplatin resistance in ovarian cancer treatment." (PMID 36551554, 2022). "Additionally, the protein levels of XRCC2, XRCC4 and XRCC9 were also showed higher expression in IOSE cells as compared with ES2 and OVCAR3 ovarian cancer cells, which was corresponding to the results of mRNA." (PMID 34539898, 2021). "Indeed, the reciprocal immunoprecipitation of XRCC4 and LIG4 confirm that lactate markedly enhanced the interaction between XRCC4 and LIG4, with lactate treatment strongly promoting the interaction, and LDHi treatment markedly suppressing the interaction, respectively, in ovarian cancer cells." (PMID 41462961, 2025). "Therefore, XRCC4 may not be used as a clear indicator of the prognosis of ovarian cancer." (PMID 34539898, 2021). "Furthermore, XRCC2, XRCC4 and XRCC9 displayed elevated mRNA and protein levels in normal ovarian cell line, as compared to ovarian carcinoma cell lines." (PMID 34539898, 2021).
esophageal cancer (5 papers, 2013 to 2024). A primary or metastatic malignant neoplasm involving the esophagus. "Genetic variants of XRCC4 were associated with susceptibility to esophageal cancer, and high expression of XRCC4 participated in radio-resistance in patients with esophageal cancer." (PMID 32258128, 2020).
gastric cancer (5 papers, 2013 to 2022). A primary or metastatic malignant neoplasm involving the stomach. "Currently, biomarkers are used for the clinical diagnosis and prognosis in a variety of cancers, such as lung, breast, and gastric cancers Therefore, XRCC4/5/6 can be used as novel diagnostic and prognostic biomarkers for LUAD." (PMID 34486486, 2021). "In a study, miR-129-3p directly inhibited the expression of SUMO-activated enzyme subunit 1 (SAE1) by targeting 3'UTR and also suppressed the zoylation of XRCC4, leading to more DNA damage in gastric cancer cells and inhibition of the proliferation, migration and invasion of gastric cancer cells." (PMID 34326688, 2021). "Alternatively, miR‐129‐3p has been reported to inhibit the NHEJ pathway—via the inhibition of XRCC4 SUMOylation—by targeting the SUMO‐activating enzyme SAE1 and repressing the progression of human gastric cancer." (PMID 35000298, 2022).
oral cancer (5 papers, 2013 to 2022). "The recessive missense XRCC4 polymorphism at codon 247 (c.739G>T, pAla247Ser) (SNP rs3734091) is associated with development of oral cancer, HCC, and breast cancer, in particular increasing the risk of developing triple-negative breast cancer." (PMID 28684677, 2017). "XRCC4 D allele polymorphism (SNP rs28360071) is associated with oral cancer, and this polymorphism was found to be significantly associated with cancer risk in a meta-analysis." (PMID 28684677, 2017). "In addition to these two novel SNPs, the XRCC4 codon 247 (rs3734091) was also associated with increased oral cancer risk." (PMID 25705582, 2015). "As for oral cancer, those who had heterozygous del/ins at XRCC4 intron 3 (rs28360071) showed a 1.57-fold (95% confidence interval = 1.12-2.21) increased risk of oral cancer compared to those with ins/ins." (PMID 25705582, 2015).
astrocytoma (4 papers, 2013 to 2016). "Furthermore, polymorphisms in CHAF1A and XRCC1 are associated with the risk of astrocytoma, whereas SNPs in EME1, ATM, GLTSCR1, and XRCC4 are associated with susceptibility to non-astrocytoma subtypes." (PMID 27613841, 2016). "In conclusion, we investigated an association between XRCC3, XRCC4 and XRCC5 gene polymorphism and the risk and prognosis of astrocytoma in Chinese Han population." (PMID 27852033, 2016). "In this study, we want to explore the relationship between DNA repair genes (XRCC3, XRCC4 and XRCC5) and prognosis of astrocytoma in the Chinese Han population." (PMID 27852033, 2016). "So, we want to determine the effect of DNA repair genes (XRCC3, XRCC4 and XRCC5) on the prognosis of astrocytoma in our research." (PMID 27852033, 2016). "Significant down-regulation of XRCC4 was found in grade II, III, IV of astrocytoma compared to normal brain tissues and decreased expression of XRCC4 was significantly associated with a poor prognosis (P < 0.05)." (PMID 23663450, 2013).
Fanconi anemia (4 papers, 2014 to 2025). Fanconi anemia (FA) is a hereditary DNA repair disorder characterized by progressive pancytopenia with bone marrow failure, variable congenital malformations and predisposition to develop hematological or solid tumors. "Indeed, tumors and cytopenia observed in some XRCC4 patients also remind cancer susceptibility in LIG4 deficiency, Fanconi anemia [MIM:PS227650], Ataxia-Teleangiectasia [MIM#208900], and more broadly, genomic instability syndromes such as Mosaic Variegated Aneuploidy [PS257300]." (PMID 40114033, 2025). "Proteins other than BRCA2 implicated in homologous recombination or the Fanconi anemia repair pathway, like BRCA1, RAD51, PALB2, XRCC3, FANCI, or FANCD2, were at most modestly affected, as were non-homologous end joining proteins like KU80, KU70, and XRCC4." (PMID 28575672, 2017).
medulloblastoma (4 papers, 2013 to 2017). A malignant, invasive embryonal neoplasm arising from the cerebellum.
microcephalic primordial dwarfism (4 papers, 2021 to 2025). Primordial dwarfism with microcephaly. "Genetic variants and mutations of XRCC4 contribute to cancer susceptibility, and XRCC4 is also the causative gene of microcephalic primordial dwarfism (MPD) in humans." (PMID 35000298, 2022). "Several deleterious mutations in the XRCC4 gene have been reported in humans (see de Villartay, 2015 for review), most of which are associated with microcephalic primordial dwarfism (MPD), gonadal failure, early-onset metabolic syndrome, and cardiomyopathies." (PMID 34519267, 2021). "Our findings contribute to elucidating the XRCC4 functions and the role of abnormal XRCC4 in diseases, including cancers and microcephalic primordial dwarfism, and may help in developing XRCC4‐targeted drugs for humans and cats." (PMID 35000298, 2022).
triple-negative breast carcinoma (4 papers, 2014 to 2024). An invasive breast carcinoma which is negative for expression of estrogen receptor (ER), progesterone receptor (PR), and human epidermal growth factor receptor 2 (HER2). "pointed out that XRCC4 gene knockout could enhance the sensitivity of triple-negative breast cancer cells to ionizing radiation, which could be used as a new predictor of radiation sensitivity and expected to become a target of triple-negative breast cancer." (PMID 39669558, 2024).
viral infection (4 papers, 2012 to 2026). "Lung XRCC4 knockdown mice displayed faster body weight loss and poorer survival than control mice during viral infection." (PMID 33846346, 2021). "We established stable cell lines from the XRCC4-KO HCT116 cell line expressing either FLAG-XRCC4 WT or FLAG-XRCC4 T308A via viral infection." (PMID 41513635, 2026). "Some cytoplasmic forms of LIG4 have been reported in response to specific viral infections and the LIG4 protein has been shown to regulate the nuclear localization of XRCC4, suggesting that XRCC4 may potentially interact with ATM in the cytoplasm in the case of specific mutations of LIG4." (PMID 36551628, 2022). "Thus it appears that DNA-PKcs and Ku70 exert a negative effect on viral infection; however, knockdown of DNA Ligase IV or XRCC4 decreased viral yields and suggests that some components of the C-NHEJ pathway may be important for viral replication." (PMID 22912580, 2012).